KDM2A (lysine demethylase 2A)
Description:
Histone demethylase that specifically demethylates 'Lys-36' of histone H3, thereby playing a central role in histone code. Preferentially demethylates dimethylated H3 'Lys-36' residue while it has weak or no activity for mono- and tri-methylated H3 'Lys-36'. May also recognize and bind to some phosphorylated proteins and promote their ubiquitination and degradation. Required to maintain the heterochromatic state. Associates with centromeres and represses transcription of small non-coding RNAs that are encoded by the clusters of satellite repeats at the centromere. Required to sustain centromeric integrity and genomic stability, particularly during mitosis. Regulates circadian gene expression by repressing the transcriptional activator activity of CLOCK-BMAL1 heterodimer and RORA in a catalytically-independent manner.
Synonyms: CXXC8; FBL11; FBL7; FBXL11; JHDM1A; KIAA1004; LILINA; DKFZP434M1735; FLJ00115
Tractability: Small molecule: a structure with a bound ligand is known; a high-quality ligand is known; it has a high-quality binding pocket; it belongs to a druggable protein family. PROTAC: UniProt records ubiquitination sites on it; ubiquitination databases record sites on it; its protein half-life has been measured; a small molecule that binds it is known.
Target class: Epigenetic regulator; Jumonji domain-containing; Eraser; Lysine demethylase
Gene: Protein-coding gene on chromosome 11 (67,119,263 to 67,258,082, forward strand). Ensembl gene ENSG00000173120.
Subcellular location: Nucleus, nucleoplasm; Chromosome
Subcellular location (Human Protein Atlas): Nucleoplasm
Pathways (Reactome):
Chromatin organization: HDMs demethylate histones
Gene Ontology:
Molecular function: histone H3K36 demethylase activity; histone H3K36me/H3K36me2 demethylase activity; protein binding; unmethylated CpG binding; zinc ion binding; histone demethylase activity; transcription coregulator activity; DNA binding
Biological process: circadian regulation of gene expression; double-strand break repair via nonhomologous end joining; negative regulation of transcription by RNA polymerase II; regulation of circadian rhythm; chromatin remodeling; regulation of transcription by RNA polymerase II; SCF-dependent proteasomal ubiquitin-dependent protein catabolic process
Cellular component: chromosome; nucleoplasm
Genetic constraint (gnomAD): Loss-of-function variants: 2 observed, 110.25 expected, observed/expected ratio (o/e) 0.0181, 90% interval 0.006 to 0.057. The upper end of that interval is the gene's LOEUF score, 0.057, which puts it in group 1 of 6, group 1 being the genes least tolerant of losing a copy. Missense variants: 688 observed, 1,395.3 expected, observed/expected ratio (o/e) 0.49, 90% interval 0.46 to 0.52. Synonymous variants: 466 observed, 517.35 expected, observed/expected ratio (o/e) 0.9, 90% interval 0.83 to 0.97.
Homologues: Orthologues: chimpanzee KDM2A (100% identical), macaque KDM2A (99% identical), dog KDM2A (99% identical), guinea pig KDM2A (98% identical), pig KDM2A (98% identical), rabbit KDM2A (98% identical), mouse Kdm2a (97% identical), rat Kdm2a (97% identical), tropical clawed frog kdm2a (67% identical), zebrafish kdm2ab (54% identical), zebrafish kdm2aa (52% identical), Caenorhabditis elegans jmjd-1.2 (13% identical), and 1 more. Paralogues in human: KDM2B (54% identical), PHF8 (20% identical), KDM7A (17% identical), PHF2 (17% identical).
Diseases named in the same sentence as KDM2A in open-access papers:
KDM2A is named in the same sentence as 87 diseases in open-access papers, as found by Europe PMC text mining. Sharing a sentence is not in itself a finding about the gene and the disease. The quoted sentences say what the papers report.
breast carcinoma (32 papers, 2014 to 2025). "Increase of stromal KDM2A is associated with advanced tumour stage and poor clinical outcome in breast cancer patients." (PMID 33024266, 2021). "In this study, we provide the first evidence that KDM2A is upregulated in human breast cancer stroma and is associated with poor clinical outcome." (PMID 33024266, 2021). "They further analyzed the Cancer Genome Atlas (TCGA) data on DNA copy number, mutation and overall survival for 976 breast cancer sample and found that the short isoform of KDM2A was more abundant in a subset of the cancers investigated." (PMID 29246117, 2017). "Here, we showed that expression of lysine demethylase 2A (KDM2A) is markedly increased in human breast cancer and its overexpression is associated with tumor progression and poor prognosis." (PMID 27029061, 2016). "Univariate log-rank analysis showed tumor size, nodal status, stage and KDM2A expression are associated with the survival of breast cancer patients." (PMID 27029061, 2016). "In the present study, we investigated the expression of KDM2A in breast cancer tissues and examined its association with clinicopathological features." (PMID 27029061, 2016). "More importantly, analysis of the association of KDM2A with survival of breast cancer patients in two public databases that included more than 3,500 patients also indicated that high expression of KDM2A is linked with poor survival." (PMID 27029061, 2016). "Therefore, this study aimed to clarify the underlying molecular mechanism of IL-6-regulated KDM2A in enhancing chemoresistance in breast cancer." (PMID 37821959, 2023). "Mild starvation due to low concentrations of an inhibitor of glycolysis, 2-deoxy-D-glucose, activates AMP-activated protein kinase (AMPK) and lysine-specific demethylase 2A (KDM2A) to reduce rRNA transcription and cell proliferation in breast cancer cells." (PMID 40427554, 2025). "This mild starvation condition also reduces proliferation of breast cancer cells in a KDM2A-dependent manner." (PMID 40427554, 2025). "We previously showed that starvation by 2-deoxy-D-glucose (2DG) reduced the rRNA transcription and cell proliferation of breast cancer cells in a KDM2A–dependent manner." (PMID 40427554, 2025). "Identification of responsible phosphatase(s) and kinase(s) that control the phosphorylation status of Ser731 of KDM2A would open an avenue for a novel target of breast cancer therapy." (PMID 40427554, 2025). "The reductions in rRNA transcription and cell numbers were suppressed by either KDM2A or PHF8 knockdown (KD) in the breast cancer cell line MCF-7." (PMID 40427554, 2025). "Identification of the enzyme(s) that control the phosphorylation state of Ser731 of KDM2A would provide a novel target for breast cancer therapy." (PMID 40427554, 2025). "Here, we found that PHD finger protein 8 (PHF8) interacted with KDM2A and contributed to the reduction in rRNA transcription and cell proliferation by 2-deoxy-D-glucose in a breast cancer cell line, MCF-7." (PMID 40427554, 2025). "Gallic acid has been shown to suppress rRNA transcription via reactive oxygen species-mediated activation of Lysine-specific histone demethylase 2A (KDM2A) in breast cancer MCF-7 cells." (PMID 39410048, 2024). "Enrichment analysis of immune cells/stromal cells using TCGA-breast cancer RNA-seq data unveiled a positive correlation between stromal KDM2A and the abundance of M2 macrophages." (PMID 37821959, 2023). "To investigate the relationship between stromal KDM2A and infiltrated M2 macrophages, we analyzed breast cancer samples with high immune/stromal scores from TCGA." (PMID 37821959, 2023). "Breast cancer-secreted IL-6 was found to orchestrate a chain of events, beginning with the upregulation of KDM2A in mammary fibroblasts through the STAT3/NFκB p50 axis." (PMID 37821959, 2023). "KDM2A-expressing CAFs dominantly secreted the CXCR2-associated chemokines to promote M2 macrophage polarization and enhance paclitaxel resistance in breast cancer." (PMID 37821959, 2023).
breast carcinoma (continued). "Our previous study has shown that KDM2A promotes angiogenesis, maintains cancer stemness, and induces drug resistance in breast cancer by regulating jagged-1(JAG-1) and SRY-box transcription factor 2 (SOX-2)." (PMID 37821959, 2023). "Our recent study found that the pro-inflammatory cytokine IL-6, released by breast cancer cells, can increase the expression of KDM2A, thereby promoting the transformation of CAFs." (PMID 37821959, 2023). "We demonstrated that KDM2A-expressing fibroblasts play an important role in cancer development and contribute to increased resistance to paclitaxel in breast cancer by promoting M2-macrophage polarization." (PMID 37821959, 2023). "Cytokines such as IL-6 and tumor necrosis factor-alpha (TNF-α) released by breast cancer cells can stimulate the expression of KDM2A in fibroblasts." (PMID 36291773, 2022). "A study suggested that KDM2A inhibits breast cancer cell migration and invasion in vitro, possibly by regulating the transcriptional activity of E2F1." (PMID 36291773, 2022). "Previous studies have demonstrated that serum and glucose deprivation induce KDM2A-mediated demethylation of H3K36me2 to decrease rRNA transcription and cell proliferation in breast cancer." (PMID 35697678, 2022). "This suggests that inhibition of KDM2A expression is a potential therapeutic target in breast cancer." (PMID 36291773, 2022). "Among the numerous PKMT and PKDM that have been identified so far, SET6, SMYD2, SMYD3, LSD1, and KDM2A have been shown to regulate breast cancer." (PMID 35216622, 2022). "Stromal KDM2A plays an oncogenic role in breast cancer and inhibition of KDM2A reduces fibroblast senescence and suppresses tumour growth." (PMID 33024266, 2021). "In breast cancer, KDM2A was found to be highly expressed and significantly correlated with shortened survival of breast cancer patients." (PMID 34391411, 2021). "Our previous study demonstrated that lysine demethylase 2A (KDM2A) enhances stemness in breast cancer cells." (PMID 33024266, 2021). "KDM2A activity decreased rRNA transcription and the proliferation of breast cancer cells, such as MCF-7 cells, in response to glucose starvation, the anti-diabetic drug metformin, and the food-additive gallic acid [3,4,5-trihydroxybenzoic acid]." (PMID 35053178, 2021). "Studies have shown that KDM2A as a lysine demethylase was highly overexpressed in many cancers, such as breast cancer, gastric cancer, lung cancer and hepatoma." (PMID 34079757, 2021). "Co-culture of MDA-MB-231 and MCF-7 breast cancer cells with immortalised normal human mammary fibroblasts (RMF-EG) increased KDM2A expression in the fibroblasts." (PMID 33024266, 2021). "We previously demonstrated that gallic acid reduces rRNA transcription and impacts the proliferation of MCF-7 breast cancer cells in a KDM2A-dependent manner." (PMID 35053178, 2021). "An increasing number of studies have described that KDM2A exerts an oncogenic role in a wide range of tumor types, including breast cancer, gastric cancer and lung cancer, and can enhance the growth and motility of cancer cells to promote tumor progression." (PMID 34391411, 2021). "In breast cancer, KDM2A is highly expressed in myoepithelial cells which have been reported to have anti-tumor properties." (PMID 34220955, 2021). "KDM2A has been reported to be upregulated and induces proliferation in lung, gastric and breast cancer." (PMID 34220955, 2021). "Further, we found that glucose depletion activates AMP-activated protein kinase (AMPK), which is required for KDM2A to reduce rRNA transcription and cell proliferation of breast cancer cells." (PMID 33050392, 2020). "We found that gallic acid activated KDM2A to reduce rRNA transcription and cell proliferation in breast cancer MCF-7 cells." (PMID 33050392, 2020).
breast carcinoma (continued). "We also found that glucose depletion activates AMPK, and then KDM2A to reduce rRNA transcription and cell proliferation of breast cancer cells." (PMID 31822720, 2019). "We further analyzed the levels of HP1γ and KDM2A mRNAs in breast cancer cell lines, using publically available databases." (PMID 31413816, 2019). "We previously showed that the KDM2A-dependent reduction of rRNA transcription by starvation reduces proliferation of breast cancer cells." (PMID 31822720, 2019). "We showed that KDM2A and HP1γ are expressed in breast cancer tissues, including TNBCs, and that KDM2A with HP1γ reduced rRNA transcription and cell proliferation on glucose starvation in a TNBC line MDA-MB-231." (PMID 31413816, 2019). "In comparison to KDM2A-LF, KDM2A-SF is strongly overexpressed in multiple breast cancer cell lines, exhibits proliferative properties and its knockdown inhibits breast cancer cell growth." (PMID 30059280, 2018). "In further support of our data, KDM2A depletion was shown to increase the sensitivity of breast cancer cells to cisplatin-induced DNA damage." (PMID 29662616, 2018). "Unlike KDM2A-LF that has been shown to repress rRNA genes under stress conditions, KDM2A-SF has been recently shown promote proliferation by activating rRNA genes in the MCF-7 breast cancer cells." (PMID 30059280, 2018). "KDM2A promotes stemness and angiogenesis of breast cancer, and promotes silencing of tumor suppressor genes in breast cancer." (PMID 30059280, 2018). "Our previous study demonstrated that lysine demethylase 2A (KDM2A) functions as an oncogene in breast cancer by promoting cancer stemness and angiogenesis via activation of the Notch signaling." (PMID 28785073, 2017). "Taken together, we demonstrate for the first time that TET2 is a direct repression target of KDM2A and reveal a novel mechanism by which KDM2A promotes DNA methylation and breast cancer progression via the inhibition of a DNA demethylase." (PMID 28785073, 2017). "As such, it has been shown to promote tumourigenesis in lung and gastric cancers, and more recently an oncogenic isoform of KDM2A has been identified in breast cancer." (PMID 28304334, 2017). "Taken together, we conclude that KDM2A functions as an oncogene in breast cancer by upregulating JAG1 to promote stemness, chemoresistance and angiogenesis." (PMID 27029061, 2016). "Collectively, we conclude that KDM2A functions as an oncogene in breast cancer by upregulating JAG1 to promote stemness, chemoresistance and angiogenesis." (PMID 27029061, 2016). "To clarify how KDM2A enhances stem-like properties of breast cancer cells, we investigated the alteration of stemness markers after KDM2A depletion and identified SOX2 as a key mediator." (PMID 27029061, 2016). "Our results suggested that KDM2A upregulates JAG1 to promote NOTCH activation which directly activates the transcription of SOX2 gene in breast cancer cells." (PMID 27029061, 2016). "We showed for the first time that KDM2A binds to the JAG1 promoter to increase its expression in breast cancer cells." (PMID 27029061, 2016). "Silencing KDM2A using small interfering RNAs increased the invasion and migration of breast cancer cells by suppressing a subset of matrix metalloproteinases, such as MMP-2, MMP-9, MMP-4 and MMP-15." (PMID 26430963, 2015). "Here we show that KDM2A is strongly expressed in myoepithelial cells (MEPC) in breast cancer tissues by immunohistochemistry." (PMID 25029110, 2014). "Taken together, these results show that KDM2A represses invasion and migration of breast cancer cells, and depletion of KDM2A enhances these processes." (PMID 25029110, 2014). "Our results indicate that KDM2A represses migration and invasion of breast cancer cells, and inhibits angiogenic tubule formation by endothelial cells." (PMID 25029110, 2014).
breast carcinoma (continued). "Silencing KDM2A with small interfering RNAs demonstrated increased invasion and migration of breast cancer cells by suppressing a subset of matrix metalloproteinases (MMP-2, -9, -14 and -15), as seen by real-time PCR." (PMID 25029110, 2014). "Further, the fact that KDM2A is expressed in myoepithelial cells requires further investigation of KDM2A as a prognostic marker, in angiogenesis and metastasis of breast cancer." (PMID 25029110, 2014). "Here we studied the expression and function of KDM2A in human breast cancers and find that the expression of KDM2A is predominantly in the myoepithelial cells." (PMID 25029110, 2014). "Expression of KDM2A in MEPCs raised the possibility of a similar role for KDM2A in breast cancer cells, hence we examined the role of KDM2A in various cellular processes." (PMID 25029110, 2014). "KDM2A/JHDM1A/FBXL11 is a JmjC-containing histone demethylase that targets mono- and dimethylated Lys36 residues of Histone H3; its function in breast cancer is not fully understood." (PMID 25029110, 2014). "The effect of deletion of the A region in KDM2A was also examined in breast cancer MCF-7 cells." (PMID 40427554, 2025). "Previously, we reported that KDM2A was expressed in breast cancer tissues." (PMID 40427554, 2025). "Here, we showed that KDM2A together with PHF8 controlled rRNA transcription in breast cancer cells." (PMID 40427554, 2025). "Therefore, this study aimed to elucidate the underlying molecular mechanism of IL-6 in regulating KDM2A expression in CAFs and KDM2A-mediated paclitaxel resistance in breast cancer." (PMID 37821959, 2023). "In breast cancer, KDM2A can promote DNA methylation by inhibiting the expression of tet-eleven translocation 2 (TET2), thereby suppressing the expression of epithelial cell adhesion molecule (EpCAM) and E-Cadherin, further enhancing the tumor invasion capacity of breast cancer." (PMID 37821959, 2023). "Interestingly, KDM2A expression in cancer-associated fibroblast promotes carcinogenesis and inhibition of KDM2A suppress the tumor growth via inhibiting PDL1 expression in breast cancer fibroblast cell lines." (PMID 36048239, 2022). "KDM2A activates the Notch signaling pathway to enhance the stemness of breast cancer cells." (PMID 35216622, 2022). "Therefore, creating novel therapeutic agents for breast cancer by targeting KDM2A requires more in-depth research." (PMID 36291773, 2022). "Furthermore, KDM2A knockout significantly increases TET2 expression in various breast cancer cell lines." (PMID 35223782, 2022). "In this context, breast cancer cell-derived cytokines can stimulate the expression of KDM2A in normal human breast fibroblasts, and KDM2A can induce fibroblast senescence and release more cytokines to promote the proliferation of breast cancer cells, thus forming a vicious cycle." (PMID 36291773, 2022). "In addition, breast cancer patients with strong stromal KDM2A expression have a shorter disease-specific survival (DSS) (p = 0.0012) and metastasis-free survival (MeFS) (p < 0.0001)." (PMID 33024266, 2021). "This speculation is consistent to the finding of the continuous expression of KDM2A during carcinogenesis in breast carcinomas." (PMID 33050392, 2020). "We previously proposed that the reduction of rRNA transcription by KDM2A may be applied to the treatment of breast cancers." (PMID 33050392, 2020). "Because KDM2A has the activity to reduce rRNA transcription and proliferation of breast cancer cells, we previously proposed that the reduction of rRNA transcription by KDM2A specifically in cancer cells may be applied to the treatment of breast cancers." (PMID 33050392, 2020). "Acceleration of cell growth by KDM2A was also observed in breast cancer cells." (PMID 33050392, 2020).